TXNIP (thioredoxin interacting protein)
Diseases named in the same sentence as TXNIP in open-access papers (continued):
Sharing a sentence is not in itself a finding about the gene and the disease.
breast carcinoma (continued). "Researchers have also shown that low level of TXNIP expression is related to poor prognosis in patients with breast cancer, and so, TXNIP may be of great importance in providing new targets for the treatment of patients with TNBC." (PMID 33194655, 2020). "Because TXNIP is an effective tumor suppressor, it is often found to be expressed at low levels in different kinds of tumors; in particular, TXNIP expression levels in human breast cancer MCF-7 cells are markedly decreased." (PMID 33194655, 2020). "Besides miR-200 family, we were also interested in analyzing miR-373 that has been described to promote EMT and metastasis by suppressing thioredoxin-interacting protein (TXNIP) in breast cancer." (PMID 26943577, 2016). "However, despite the ongoing evaluation of TXNIP as a therapeutic target, little is known about the prognostic value of TXNIP in breast cancer patients receiving anti-Her-2 treatment and its relevance to overall survival (OS)." (PMID 25605021, 2015). "Moreover, TXNIP expression increased significantly following treatment of the human breast cancer cell lines BT474 and SK-BR-3 with a Her-1/2 inhibitor." (PMID 25605021, 2015). "Taken together, our findings suggest that TXNIP plays a critical role in anti-Her-1/Her-2 treatment and may be a potential prognostic marker in breast cancer." (PMID 25605021, 2015). "Also, using a tissue array, we found decreased expression of TXNIP and p27 in breast cancer tissue, compared with NCTs." (PMID 25605021, 2015). "However, little is known regarding the prognostic value of TXNIP in clinical breast cancer patients with anti-Her-2 treatment." (PMID 25605021, 2015). "Taken together, our results suggest that TXNIP may enhance lapatinib-induced inhibition of cell proliferation in Her-1/2 positive breast cancer cell lines." (PMID 25605021, 2015). "In conclusion, TXNIP may interrupt Her receptor family mediated oncogenic pathways thereby increasing OS in breast cancer patients." (PMID 25605021, 2015). "The levels of miR-373, TXNIP, HIF1α and TWIST were significantly associated with the TNM stage and lymph node metastasis, but not with other tested clinical characteristics in patients with breast cancer." (PMID 26196741, 2015). "TXNIP may also be a prognostic marker of breast cancer response to anthracycline-based chemotherapy." (PMID 25605021, 2015). "Our findings suggest TXNIP plays a critical role in anti-Her-1/Her-2 treatment and may be a potential prognostic marker in breast cancer." (PMID 25605021, 2015). "In breast cancer, histone alteration may be a systematic mechanism of TXNIP transcriptional regulation, as evidenced by the rapid development of TXNIP mRNA in breast cancer cell lines which was seen when a histone deacetylase inhibitor was used to improve acetylation." (PMID 36366411, 2022). "Besides, breast cancer 1 (BRCA1)-deficient cells were sensitized to the BET inhibitor, which reversed the MYC/TXNIP axis by inhibiting the activity of thioredoxin and elevating cellular oxidative stress, causing DNA damage that led to the death of BRCA1-deficient breast cancer cells." (PMID 35547739, 2022). "In general, TXNIP protein was present only in a small proportion of primary tumor samples and in these cases was differently expressed depending on tumor stage and subtype (e.g., renal cell carcinoma, thyroid cancer, breast cancer, and ductal pancreatic cancer)." (PMID 33081035, 2020). "In a previous study, we found TXNIP activation by UNC0642, an inhibitor of histone methyltransferase G9A, significantly inhibited MDA-MB-231 breast cancer cell proliferation in vitro and tumor growth in vivo." (PMID 40175348, 2025). "And estrogen enhances the Warburg effect in breast cancer by activating the IRE1 signaling pathway of the UPR to suppress TXNIP expression, elucidating the pathway by which the estrogen/ERα–IRE1–TXNIP axis stimulates tumor cell growth and proliferation." (PMID 39080273, 2024).
breast carcinoma (continued). "To investigate the effects of key ferroptosis-related genes (TXNIP, SLC2A1, and ATF3) on ferroptosis in breast cancer cells, we measured the levels of GSH, MDA, and Fe2+ in the cells." (PMID 38244591, 2024). "TXNIP and ATF3 are tumor suppressor genes in breast cancer, and their upregulation can trigger the ferroptosis mechanism and suppress the growth of breast cancer cells." (PMID 38244591, 2024). "Three key ferroptosis-related genes (TXNIP, SLC2A1, ATF3) closely related to the occurrence, development, and prognosis of breast cancer were identified using machine learning algorithms." (PMID 38244591, 2024). "We conducted in vitro transfections with siRNA-SLC2A1, TXNIP overexpression plasmids, and ATF3 overexpression plasmids to further investigate the effects of key ferroptosis-related genes on ferroptosis in breast cancer cells." (PMID 38244591, 2024). "By binding to TXNIP promoter in E-box -containing region, c-Myc competes with MondoA and represses TXNIP expression in TNBC, indeed a c-Mychigh/TXNIPlow signature correlates with poor OS specifically in this subclass of breast cancer." (PMID 37794178, 2023). "To determine whether the inverse relationship between TXNIP and Myc transcriptional programs is restricted to cell lines, we downloaded the gene expression data from 1,904 breast tumors annotated in the Molecular Taxonomy of Breast Cancer International Consortium (METABRIC) dataset." (PMID 36930677, 2023). "TXNIP expression was detected in HT-29 and HCT 116 cells (both colon carcinoma), DU4475 (breast cancer), and PaCa 5072 and PaCa 5061 cells (both pancreatic carcinoma)." (PMID 33081035, 2020). "As for the protective factors (IL1RL1, TXNIP, and APP), IL1RL1 was similarly identified to function as a tumor suppressor in mammary tumor." (PMID 32328125, 2020). "In this study, we demonstrate that miR-373 stimulates breast cancer cell EMT and metastasis by directly inhibiting TXNIP." (PMID 26196741, 2015). "The silencing of TXNIP induced EMT and promoted migration and invasion in breast cancer cells, similar to the effects of miR-373 over-expression." (PMID 26196741, 2015). "For example, Oncomine analysis of breast cancer data showed that ARRDC2/3/4 and TXNIP appear among the genes most downregulated between normal and cancer tissue, whereas ARRB2 appears among the genes most upregulated." (PMID 23236378, 2012). "We have recently shown that glucose regulates ROS production through TXNIP regulation and TRX activity in breast cancer derived cells." (PMID 21910912, 2011). "As a result, both NUF2 and TXNIP protein levels were downregulated in breast cancer cells lacking STARD7." (PMID 40443279, 2025). "Additionally, estrogen activates the IRE1 pathway of the UPR, suppressing thioredoxin interacting protein (TXNIP) expression, which amplifies the Warburg effect and promotes breast cancer cell proliferation." (PMID 41209558, 2025). "Among them, TXNIP and ATF3 were significantly downregulated in breast cancer tissues compared to adjacent tissues (P < 0.001), while SLC2A1 was significantly upregulated in breast cancer tissues compared to adjacent tissues (P < 0.001)." (PMID 38244591, 2024). "Similarly, albeit through a different mechanism, TXNIP mediates the internalisation and degradation of EGFR, decreasing the migratory capacity of breast cancer cells." (PMID 37794178, 2023). "A Mychigh/TXNIPlow gene signature is clinically significant as it correlates with poor clinical prognosis in triple-negative breast cancer (TNBC) but not in other subtypes of breast cancer, suggesting a functional relationship between Myc and TXNIP." (PMID 36930677, 2023). "TXNIP expression was not significantly correlated with gender, age, and breast cancer stage (N), but was negatively correlated with Ki-67 expression, tumor nodule number, and distant metastasis." (PMID 35414060, 2022).
breast carcinoma (continued). "Thus, through its influence on AMPK and TXNIP, DASA-58 treatment can further accelerate glucose metabolism in breast cancer and HNSCC in combination with lowering OxPhos even further." (PMID 35054968, 2022). "A significant negative correlation was found between TXNIP and Her-2 status using the breast cancer tissue-array (n=150) (r=-0.334, P<0.001), which was again validated in the external cohort (n=101) (r=-0.422, P<0.001)." (PMID 25605021, 2015). "Using a tissue microarray, we detected TXNIP and p27 expression in breast cancer tissue, as well as corresponding noncancerous tissues." (PMID 25605021, 2015). "In this study, we found a significant negative correlation between TXNIP and Her-2 status in breast cancer, and showed that inhibition of the Her-1/2 pathway resulted in increased TXNIP expressions." (PMID 25605021, 2015). "A few genes previously reported to be induced by acidosis in breast cancer cells, including TXNIP, ARRDC4 and EGR2, were also noted to be induced in both HUVEC/Vector and HUVEC/GPR4 cells." (PMID 23613998, 2013). "The purpose of this work was to study the prognostic influence in breast cancer of thioredoxin reductase 1 (TXNRD1) and thioredoxin interacting protein (TXNIP), key players in oxidative stress control that are currently evaluated as possible therapeutic targets." (PMID 20584310, 2010). "However, it is still unclear whether TXNIP, SLC2A1, and ATF3 affect the growth of breast cancer cells by regulating the ferroptosis mechanism." (PMID 38244591, 2024). "Supporting this hypothesis, TXNIP mRNA expression is inversely correlated with three critical regulators of proton export that function to increase intracellular pH: monocarboxylate transporter (MCT) 1 in lung cancer, MCT4 in breast cancer and sodium-hydrogen antiporter 1 (NHE1) in brain cancer." (PMID 30717828, 2019). "Our previous work demonstrated that low TXNIP expression correlates with poor clinical outcomes in TNBC, but not in other breast cancer subtypes." (PMID 36930677, 2023).
type 2 diabetes (58 papers, 2012 to 2025). "For example, some of our loci, mapping to ABCG1, CPT1A and TXNIP, have been associated with lipid and metabolic traits such as triglycerides, BMI, and type 2 diabetes." (PMID 41361833, 2025). "Elevated levels of TXNIP have been demonstrated to trigger apoptosis in β-cells, while a deficiency in TXNIP has shown protective effects against both type 1 and type 2 diabetes by enhancing β-cell survival." (PMID 38397173, 2024). "When elevated, TXNIP induces β-cell apoptosis, while its deficiency protects against type I and type II diabetes by promoting β-cell survival." (PMID 37679740, 2023). "For four of the top six CpGs previously identified in a meta-EWAS of type 2 diabetes that had bidirectional 2SMR data (CpGs in TXNIP, HDAC4, SYNM and ABCG1), the observational and causal effects were consistent only at HDAC4 (cg00144180)." (PMID 37202507, 2023). "Alternatively, a deficiency of TXNIP resulted in severe hypoglycemia and hyperinsulinemia and, as a result, is therefore considered to be protective against type 1 and type 2 diabetes." (PMID 36733403, 2023). "The results from our meta-analysis included CpG sites at genes that are known to be associated with type 2 diabetes, such as TXNIP, ABCG1, SREBF1 and CPT1A, showing consistency between cross-sectional and longitudinal studies and also between ethnicities." (PMID 35169870, 2022). "In both studies, increased methylation in the ABCG1 and SREBF1 genes and decreased methylation in the TXNIP gene at baseline were associated with incident type 2 diabetes." (PMID 35169870, 2022). "Methylation site cg19693031 in gene TXNIP —previously associated with type 2 diabetes, glucose and lipid metabolism, associated with fasting glucose level (P = 1.80 × 10−8)." (PMID 33239708, 2020). "The authors estimated that 32% of the unexplained risk for future type 2 diabetes among Indian Asians compared with controls was associated with a higher methylation score based on the top five markers at TXNIP, ABCG1, SREBF1, SOCS3 and PHOSPHO1." (PMID 29164275, 2018). "TXNIP, a key player in glucose metabolism, is involved in high glucose-induced reactive oxygen species generation and mitochondrial pathway apoptosis in pancreatic β cells, which has been linked to the development and progression of type 2 diabetes." (PMID 39220230, 2024). "In addition, thioredoxin-interacting protein is associated with oxidative stress and participates in the pathogenesis of type 2 diabetes." (PMID 35401695, 2022). "The association of ABCG1, SREBF1, and TXNIP with the incidence of type 2 diabetes could be reaffirmed in an independent replication study, thus rendering these factors promising for clinical use as biomarkers." (PMID 35159278, 2022). "Adjustment for baseline BMI (model 2) and for BMI, smoking and follow-up time (model 2.1) revealed that the number of significant DMS associated with incident type 2 diabetes decreased from 76 to 4 and 3, respectively (still including the two top CpG sites at the TXNIP and ABCG1 genes)." (PMID 35169870, 2022). "At the genetic level, the association between the TXNIP allele variation, type 2 diabetes, and hypertension was previously demonstrated, and the role of TXNIP as a key modulator linking the diabetogenic and vascular pathways behind metabolic conditions has been discussed." (PMID 33239708, 2020). "Similarly, we identified relevant protein associations for cg19693031 (TXNIP gene) previously associated with type 2 diabetes and cg07839457 (NLRC5 gene) previously associated with immune-related proteins such as CD48 antigen or traits such as rheumatoid arthritis." (PMID 41361833, 2025). "In addition, the correlation of the human insulin/glucose clamp study revealed that inversed correlation of TXNIP expression and insulin dependent glucose uptake in skeletal muscle and TXNIP expression are associated with the risk of the pathogenesis of type 2 diabetes (T2D) in humans." (PMID 32824669, 2020).
type 2 diabetes (continued). "Recent studies have shown an association between DNA hypomethylation of the TXNIP gene and type 2 diabetes mellitus (T2DM)." (PMID 32609762, 2020). "The replicated associations for type 2 diabetes implicated genes including ABCG1, CPT1A, SREBF1, and TXNIP." (PMID 37410739, 2023). "Genes annotated to CpGs that were associated with type 2 diabetes included ABCA1, ABCG1, CPT1A, SREBF1, SLC7A11, SLC7A5, and TXNIP among others (see S12 Table for full details)." (PMID 37410739, 2023). "It has been previously reported that TXNIP was upregulated in the diabetic pancreas and that low level of TXNIP was protective against type 1 and type 2 diabetes." (PMID 36733403, 2023). "Hypomethylation within TXNIP (cg19693031) and ABCG1 hypermethylation (cg06500161) have been associated with type 2 diabetes risk across individuals of multiple ancestries." (PMID 37410739, 2023). "A nested case-control study including 25,372 individuals identified five loci that were associated with future type 2 diabetes incidence, including ABCG1, PHOSPHO1, SOCS3, SREBF1, and TXNIP." (PMID 35399937, 2022). "Down-regulates TXNIP expression and intracellular calcium concentration; protects pancreatic beta cell function; and prevents type 2 diabetes and promotes its treatment." (PMID 35566359, 2022). "Results from the majority of those studies indicate that differentially methylated sites in the TXNIP, ABCG1, CPT1A and SREBF1 genes are associated with type 2 diabetes and glycaemic traits." (PMID 29164275, 2018). "Another replicated CpG site is TXNIP (cg19693031), which is shown to be hypomethylated in type 2 diabetes." (PMID 29164275, 2018). "For instance, overexpression of IAPP relative to insulin has been observed in rat models of type 2 diabetes, and TXNIP has been shown to inhibit insulin transcription while inducing IAPP transcription." (PMID 28980863, 2017). "TXNIP was also observed to be increased in patients with type II diabetes by a number of different studies." (PMID 26075098, 2015). "Thioredoxin-interacting protein (TXNIP) has been linked to cell apoptosis and inflammation in a number of diseases, including type 2 diabetes, atherosclerosis, and myocardial ischemia." (PMID 23520439, 2013). "Similarly, metformin, a frontline medication for type 2 diabetes, effectively prevents the activation of the TXNIP/NLRP-3 inflammasome by mitigating ER stress and activating AMPK in macrophages." (PMID 38790650, 2024). "While methylation in TXNIP has been associated with type 2 diabetes, it has not been associated with breastfeeding or other infant diet exposures." (PMID 34836312, 2021). "Abnormal TXNIP levels are notable, e.g., in type II diabetes, cardiovascular diseases, and tumors." (PMID 33081035, 2020). "Last but not least, cg19693031 in TXNIP has been repeatedly associated with type 2 diabetes case-control status earlier." (PMID 31197173, 2019). "In our Lifelines sample, five out of 52 included CpGs showed significant associations with type 2 diabetes (the Bonferroni-adjusted p < 0.0009 (0.05/52 CpGs)), including the loci in the ABCG1, LOXL2, TXNIP, SLC1A5 and SREBF1 genes (see a short description in ESM Box 1)." (PMID 29164275, 2018). "Despite its important function in type 2 diabetes pathogenesis, TXNIP was not identified as one of the susceptibility genes in recent GWAS studies for type 2 diabetes." (PMID 29164275, 2018). "Since TXNIP was found to be induced in β-cells in human type 2 diabetes, it will be interesting to determine whether phosphorylation of Ets1 is induced as well." (PMID 24897113, 2014). "A high TXNIP DNA methylation percentage at CpG site cg19693031 in blood has consistently been associated with lower fasting blood glucose, HbA1c and/or HOMA-IR levels, as well as a lower prevalence and a decreased risk of type 2 diabetes (T2DM) in different studies." (PMID 29077742, 2017).